RNU6-142P (RNA, U6 small nuclear 142, pseudogene)
Gene: Small nuclear RNA gene on chromosome 18 (62,731,226 to 62,731,332, reverse strand). Ensembl gene ENSG00000206746.
Homologues: Orthologues: chimpanzee U6 (100% identical), dog U6 (86% identical), guinea pig U6 (81% identical). Paralogues in human: RNU6-19P (91% identical), RNU6-26P (91% identical), RNU6-12P (90% identical), RNU6-13P (90% identical), RNU6-166P (90% identical), RNU6-25P (90% identical), RNU6-31P (90% identical), RNU6-32P (90% identical), RNU6-41P (90% identical), RNU6-820P (90% identical), RNU6-1 (89% identical), RNU6-1060P (89% identical), and 1286 more.